AHR (aryl hydrocarbon receptor)
Diseases named in the same sentence as AHR in open-access papers (continued):
Sharing a sentence is not in itself a finding about the gene and the disease.
tumor (continued). "Recent data have suggested the potential role of the AhR in regulation of the function of B cells involved in the tumor microenvironment." (PMID 29487603, 2018). "The aryl hydrocarbon receptor (AHR) is a ligand-activated transcription factor best known for mediating the toxicity and tumour-promoting properties of dioxin." (PMID 30420594, 2018). "They found antitumor immune responses to be suppressed and the proliferation and survival of tumor cells to be promoted by TDO-derived kynurenine in an autocrine/paracrine AhR-mediated manner." (PMID 29487603, 2018). "While most studies indicate that AHR functions as an oncogene, other studies propose that AHR can act as a tumor suppressor." (PMID 30254109, 2018). "From this it would be predicted that AHR inhibition would reduce multiple measures of tumor aggression." (PMID 29735912, 2018). "The immunocytochemical results indicated a role for AhR in both tumor cells and the tumor microenvironment." (PMID 29320557, 2018). "The intensity of AhR immunostaining in tumor cells varied from strong to low or moderate, depending on the individual tumor." (PMID 29320557, 2018). "More importantly, VRCZ primarily promotes the tumor development of UV-damaged KCs by P-VNO plus UVA in an AhR dependent fashion by increasing COX-2 expression." (PMID 29568008, 2018). "Local IFN-γ produced by tumor-infiltrating CD8+ T cells stimulates tumor-repopulating cell release at high levels of Kyn, which then activates AhR on the T cell surface to promote PD-1 upregulation." (PMID 30068361, 2018). "Taken together, these data suggest that the AhR affects tumor development and immune responses within tumor environments via TAMs." (PMID 29487603, 2018). "Over-expression or constitutive activation of AhR in cancer cell lines promotes tumor growth, whereas AhR inhibition in cancer cells leads to reduced cell proliferation and migration." (PMID 30563036, 2018). "Despite AHR regulation of immune-checkpoint molecules, AHR plays dual roles in tumor and immune cells." (PMID 29301348, 2018). "AhR immunostaining in peritumoral tissue ("normal" tissue adjacent to the tumor) was mainly observed in epithelial (glandular) cells and capillaries." (PMID 29320557, 2018). "The AhR has been suggested to affect cell proliferation in different tumor models and cancer cell lines." (PMID 29487603, 2018). "The AhR has been suggested to be a promoter for the initiation and progression of tumor cells, but this view is controversial." (PMID 29487603, 2018). "Recent studies have pointed to a role of AHR in a myriad of cellular mechanisms, including cell cycle, tumor invasiveness and immune function." (PMID 30501068, 2018). "Immunohistochemistry revealed the presence of AhR protein in both tumor cells (nucleus and/or cytoplasm) and the tumor microenvironment (including endothelial cells and lymphocytes)." (PMID 29320557, 2018). "Blocking the IDO/aryl hydrocarbon receptor (AhR) metabolic circuitry resulted in enhanced repression of tumor growth by apoptosis of tumor-repopulating cells." (PMID 29963055, 2018). "Knock-down of aberrantly upregulated aryl hydrocarbon receptor reduces tumor growth and metastasis of MDA-MB-231." (PMID 29320557, 2018). "For example, it is sometimes unclear if the AHR promotes or inhibits tumor aggression in any given tumor type." (PMID 29735912, 2018). "Studies on various tumor types and tumor cell lines have shown high AhR expression, suggesting that AhR is activated constitutively in tumors and facilitates their growth." (PMID 29487603, 2018). "Further in vivo studies are certainly required for assessing the ability of urolithins to control human tumor growth, and the role of AHR in mediating these effects." (PMID 30501068, 2018).
tumor (continued). "AHR plays an important role in the control of T cells, dendritic cells, gut intraepithelial lymphocytes, tumor cells and astrocytes." (PMID 29563571, 2018). "Many cancers drive tryptophan consumption and it has been shown that the primary product of tryptophan metabolism, kynurenine, is an endogenous ligand for the aryl hydrocarbon receptor, which mediates invasive tumor growth and the evasion of immunity." (PMID 30200472, 2018). "AhR immunostaining was observed in the cytoplasm of tumor cells in the 30 tumors tested, and nuclear immunostaining was also observed in 24/30 tumors (80%)." (PMID 29320557, 2018). "Aryl hydrocarbon receptor signaling has also been identified to play a crucial role in tumor immunity." (PMID 30090104, 2018). "All three human tumor cell types have significant baseline levels of AHR activity that are suppressed with AHR inhibitors." (PMID 29735912, 2018). "A tumor-promoting role of the AhR as well as its function in the immune system have been recognized." (PMID 29487603, 2018). "A direct comparison between outcomes in these system has been confounded by the use of a variety of readouts (e.g., tumor growth or migration assays), AHR modulators (inhibitors, agonists, molecular knockdowns) and tumor types." (PMID 29735912, 2018). "AHRR has also been proposed to function independently of AHR particularly in its role as a tumor suppressor." (PMID 28681081, 2018). "AhR facilitates tumor progression, disease tolerance defense, intestinal immunity, and B-cell proliferation." (PMID 29706625, 2018). "Strong evidence suggests that constitutively high AhR expression and nuclear localization can be observed in invasive tumor tissues and malignant tumor cell lines." (PMID 29487603, 2018). "In this study, we demonstrated that the VRCZ metabolites are phototoxic agents serving as an initiator of tumorigenesis, and VRCZ per se is an AhR-COX-2 activator functioning as a promoter of tumor development." (PMID 29568008, 2018). "To date, the upstream regulators of AHR in tumor cells and the specific molecular contexts in which AHR functions as an oncogene have not been identified." (PMID 30254109, 2018). "This review discusses the role of the AhR in tumor immunity and its potential mechanism of action in the tumor microenvironment." (PMID 29487603, 2018). "Here, we present a brief overview of recent investigations on the role of the AhR and potential mechanism of action (MoA) in tumor immunity." (PMID 29487603, 2018). "Proliferation analysis revealed the tumour suppressive ability of the AHR with increasing AHR expression resulting in a relative reduction in GH3 cell proliferation." (PMID 28649092, 2017). "The mechanisms governing enhanced tumour cell EMT under conditions of low AhR expression are unclear." (PMID 28195146, 2017). "Although long recognised as a xenobiotic sensing receptor, the Aryl Hydrocarbon Receptor (AHR) is now known to inhibit tumour development, partly because of its regulation of innate immune surveillance and response mechanisms." (PMID 28238104, 2017). "The presence of AHR agonists will trigger AHR translocation into the nucleus, where it can activate a genomic pathway favoring tumor survival and progression." (PMID 27752740, 2017). "Observational studies such as ours cannot clarify this, but the AHRR protein is located in the cell nucleus, and silencing of AHRR enhances tumour growth pleiotropically through increased Aryl Hydrocarbon Receptor activity." (PMID 28100713, 2017). "The AhR has tumor suppressive functions, and can be activated by distinct ligands with diverse underlying mechanisms of action including inhibition of cell cycle progression and cancer cell survival." (PMID 29194351, 2017). "On the other hand, numerous studies have shown that the AhR plays a role not only in tumor initiation but also in promotion and progression; however molecular mechanisms involved in these processes are not fully understood." (PMID 27796684, 2017).
tumor (continued). "The role of the AHR in carcinogenesis has been the subject of debate since it appears to be able to act both as an oncogene and a tumour suppressor in different cell types and contexts." (PMID 28649092, 2017). "Here, we have investigated liver regeneration after CCl4-induced damage and the liver response to the tumor inducing agent DEN in AhR-null background." (PMID 28874739, 2017). "There are conflicting reports postulating both tumour suppressive and oncogenic roles for AHR depending on cell and context specificity." (PMID 28649092, 2017). "Immunohistochemistry analysis revealed higher BNIP3 expression in the wt-CL1-5 tumours than in BafA1-treated-CL1-5 tumours or normal mouse lung, confirming that cell lines with low AhR continue to exhibit high expression of autophagy-related proteins in vivo." (PMID 28195146, 2017). "Although AHR in cytoplasm possesses tumor suppressor-like function, unfortunately, it is also likely to act as a potent inducer of malignancy." (PMID 27752740, 2017). "Taken together, these findings suggest that low levels of AhR not only promote autophagy and migration in vitro, but also metastatic tumour formation in vivo." (PMID 28195146, 2017). "AhR expression is an important parameter in carcinogenesis and tumour metastasis under physiological conditions." (PMID 28195146, 2017). "We recently showed that the selective estrogen receptor modulator raloxifene is a new AhR ligand that is effective in inducing AhR-mediated transcriptional activity and inhibiting tumor cell growth in an AhR dependent manner." (PMID 29194351, 2017). "Beyond the role as a suppressor of the AhR signaling pathway, recent reports demonstrated the potential role of the AhRR in cancer biology acting as a tumor suppressor gene." (PMID 26862745, 2016). "In conclusion, here we show that BaP is capable of promoting a HCC-like scenario in HepG2 through AhR-mediated and genotoxic mechanisms, with impairment of important liver attributions and induction of notoriously poor prognostic features in neoplasms." (PMID 26238291, 2016). "This decrease in tumor outgrowth was accompanied by a decrease in Cyp1b1, Aldh1a1, and Sox2 expression, further linking AHR activity to expression of these genes." (PMID 26984638, 2016). "This nonreceptor tyrosine kinase has been proposed to form a part of the cytoplasmic AhR complex and it significantly modulates cell behavior, including stimulation of migration and invasion of tumor cells." (PMID 27274734, 2016). "Previous reports show that PKM2 in tumor and fetal cells is expressed at much higher levels than in the adult, whereas AhR is expressed in tumor, fetal and adult tissues." (PMID 26405201, 2016). "For example, the AHR is hyper-expressed and transcriptionally active in most TNBC and IBC cell lines, and its expression is associated with tumor invasion." (PMID 26984638, 2016). "Because of the important role of AhR and its target genes in tumor formation, our results provide the basis for further studies of menadione in animal models of BP-induced cancer." (PMID 27167070, 2016). "The mechanisms underlying the role of the AhR in carcinogenesis have recently been reviewed by several authors and it has been proposed that the AhR can play both oncogenic and tumor suppressive roles in various cancer types, in a tissue-dependent manner." (PMID 27274734, 2016). "Results presented here are reminiscent of several studies demonstrating that baseline (endogenous ligand-induced) AHR activity in immortalized cells favors tumor growth or aggressive behavior." (PMID 26984638, 2016). "Now it is becoming widely recognized that AHR and its abnormal expression play an important role in multiple stages of tumor development and progression." (PMID 26392334, 2015). "The target of AHRR, the aryl hydrocarbon receptor (AHR) is a known protein that is a tumor suppressor, mediating detoxification of carcinogenic agents causing tobacco-related lung cancer." (PMID 25663950, 2015).
tumor (continued). "More recently, increasing epidemiological and experimental data provided substantial support that AhR presumably activated by endogenous ligand(s) plays an important role in tumor promotion and progression." (PMID 25669983, 2015). "In vivo imaging revealed that mice inoculated with AhR + Aldh1a1 knockdown cells had reduced tumor burden and enhanced survival than those receiving Aldh1a1-expressing sh-AhR cells." (PMID 26242870, 2015). "Independently, the AhR interacts also with various oncogenic pathways including those related to the tumor microenvironment such as alteration of extracellular matrix remodeling, promotion of angiogenesis and modulation of inflammation." (PMID 25646150, 2015). "This tumor-suppressive action of AhR is radically different from the pro-oncogenic role that AhR plays as a receptor for pro-carcinogenic ligands such as TCDD." (PMID 26264025, 2015). "AHR is overexpressed and constitutively active in a variety of tumor types, in cancer cell lines and in tumors from animal models, where it mostly shows a pro-oncogenic role." (PMID 26392334, 2015). "Regulation of IDO expression in macrophages/DC, coupled with AhR signaling in both macrophages/DC and tumor-infiltrating T cells, is well recognized for its impact on immune regulation in cancer." (PMID 26343197, 2015). "AhR expression has opposite roles in tumor progression increasing the growth of liver and stomach tumors while inhibiting intestinal carcinogenesis in mice." (PMID 26242870, 2015). "Activation of AhR, one of the ARNT-associated factors, also induces tumor formation but inhibits cancer cell invasion and metastasis." (PMID 25839165, 2015). "More recently, several studies have thus shown that the activation of PXR, AhR, Nrf2, HIF1α or PPARs play a critical role in altering the therapeutic response through reducing active drug concentration within tumor cells." (PMID 25669983, 2015). "Taken together with the sets of genes we identified in this study, we can conclude that AhR knockdown alters the expression of genes enhancing or inhibiting cancer progression; tipping the balance towards a state that counteracts tumor progression." (PMID 24932473, 2014). "The AHR is involved in the formation of tumors as AHR activation enhanced clonogenic survival and motility of tumor cells and as transgenic mice with a constitutively active AHR spontaneously develop tumors." (PMID 24657910, 2014). "It was found that NB tumors with high levels of AHR expression had higher histological grades of differentiation, suggesting that AHR expression correlated to the differentiation of NB tumor tissues." (PMID 24586395, 2014). "AhR−/− endothelial cells fail to form tube-like structures, and impaired angiogenesis limits tumor xenograft growth in AhR null mice." (PMID 25081364, 2014). "Prostate tissue analyzed by immunohistochemistry revealed that benign hyperplasia (BPH) epithelial cells possess significantly decreased AhR expression when compared to normal tissue." (PMID 24755659, 2014). "A separate study also detected significantly higher AhR expression and activation in tumor cells compared to benign glandular epithelium." (PMID 24755659, 2014). "Our data indicate that kynurenine, produced by IDO in tumor cells, activates the AHR, thereby inducing IL-6." (PMID 24657910, 2014). "Several reports have shown that AhR regulates cell migration, invasion and plasticity, all of which contribute to tumor progression." (PMID 25081364, 2014). "AHR signaling has been shown to have a functional role in tumor development, as well, and multiple AHR agonists are classified as carcinogens." (PMID 25286307, 2014). "In support of this notion, studies designed to mimic a constitutively active AhR showed a role for AhR in tumor promotion and progression." (PMID 24932473, 2014). "Biseugenol inhibits AhR expression that markedly diminishes tumor peritoneal dissemination and reduces tumor growth in a mouse model." (PMID 25226618, 2014).
tumor (continued). "Paradoxically, in some model systems, AHR is a tumor suppressor and activation of AHR protects against tumor development." (PMID 25286307, 2014). "The TDO-2-derived kynurenine then acts through the AHR in tumor cells in an autocrine manner and promotes tumor survival as well as altering the regional immune response by favoring Treg development." (PMID 25324842, 2014). "Consistently, it has recently been shown that AhR exhibits abundant amounts, and disruption of AhR suppresses the tumor growth." (PMID 25226618, 2014). "It seems that a certain level of AHR signaling is necessary for health, but excessive or insufficient AHR signaling can lead to tumor development." (PMID 25286307, 2014). "In line, knockdown of AHR in SKOV-3 cells increased proliferation of allogeneic T-cells in tumor cell/MLR cocultures." (PMID 24657910, 2014). "In conclusion AhR knockdown alters the expression of genes known to enhance or inhibit cancer progression; tipping the balance towards a state that counteracts tumor progression." (PMID 24932473, 2014). "The level of AhR expression closely correlated with increased clinical stage as well as with lymph node and distant metastasis of tumor-node-metastasis (TNM) classification, respectively." (PMID 25226618, 2014). "For example, AhR has shown tumour suppressor effects i.e., when receptor levels are down-regulated by siRNA the G1/S transition of the cell cycle and cell proliferation is promoted, suggesting a growth inhibitory role of the receptor." (PMID 23555298, 2013). "Antagonists for the AhR appear to have protective effects against carcinogen-mediated tumor initiation." (PMID 25068070, 2013). "Tryptophan-2,3-dioxygenase (TDO)-derived kynurenine promotes tumor cell survival through AhR with the progression of cell malignancy." (PMID 24330582, 2013). "As increased amount of AhR protein contributes to tumor cell aggressiveness and survival, depletion of AhR reduced orthotopic xenograft tumor growth and metastasis in vivo; making it an ideal candidate for targeted therapy." (PMID 25068070, 2013). "AhR activation by TCDD during pregnancy has also been reported to delay DMBA-induced tumor formation in adult mice." (PMID 25068070, 2013). "The full molecular mechanism of AhR-dependent tumor suppressing activity is far from being elucidated; however, some details are emerging." (PMID 23656719, 2013). "Our lab has reported that resveratrol suppresses tumor growth by inducing apoptosis in tumor cells through aryl hydrocarbon receptor (AhR) and by reciprocal regulation of SIRT1 and NF-κB signaling." (PMID 22532866, 2012). "In this respect, using microarrays it has been reported that high-risk HPV E6 and E7 oncoproteins are able to deregulate the AhR pathway in SCLC, a tumor strongly associated with the smoking habit." (PMID 22662279, 2012). "Due to its poor metabolism, TCDD activates the AhR cascade constitutively and elicits toxic responses such as impaired liver regeneration, the development of several tumor types and inflammatory skin lesions have been reported." (PMID 22254019, 2010). "AhR expression and activation is also significantly higher in tumor cells compared to benign glandular epithelium." (PMID 20140206, 2010). "Using the immune system as a model for non-dioxin-like, AhR-mediated toxicity, recent studies demonstrated that AhR-activating tryptophan metabolites influence development of T-cell subsets that control inflammation, autoimmunity, and tumor immunity." (PMID 20435556, 2010). "Surprisingly, aberrant AhR expression was detected not only in tumor samples but also in a considerable proportion of normal and hyperplastic mammary gland tissue specimens." (PMID 20565777, 2010). "In human umbilical vascular endothelial cells, AhR activation by 3-MC also exerted antiproliferative effects, as in the tumor cell lines." (PMID 20570779, 2010).